CFTR (CF transmembrane conductance regulator)
Diseases named in the same sentence as CFTR in open-access papers (continued):
Sharing a sentence is not in itself a finding about the gene and the disease.
lung disease (continued). "Among the patients within the cohort, the same parameters were evaluated separately in those who had advanced lung disease and in those who had previously undergone CFTR modulator therapy." (PMID 40531731, 2025). "We also observed improvements in the non-homogeneous ground-glass opacity pattern on chest CT, in homozygous and heterozygous patients, as well as in those previously treated with other CFTR modulators, and even in patients with advanced lung disease." (PMID 40531731, 2025). "Targeted studies on how specific inflammatory cell populations communicate in CF airways in the presence of HEMT should help address current knowledge gaps and pave the way for the development of novel therapies in CF and CFTR-related lung diseases." (PMID 40141278, 2025). "Pulmonary disease due to CFTR dysfunction in Japan has a poor prognosis because of challenges to access to the sweat test and a lack of recognition for CF." (PMID 40718166, 2025). "The multifaceted improved treatment of CF lung disease, including the introduction of CFTR modulator therapy, is likely to explain the overall reduction in ABPA over the duration of the study." (PMID 39997410, 2025). "Decreased CFTR quantity or function leads to the disruption of multiple organ functions, resulting in lung disease, gastrointestinal abnormalities, impaired growth, diabetes, infertility, and other clinical complications." (PMID 40869482, 2025). "Impaired mucociliary clearance is a direct consequence of CFTR dysfunction that plays a critical role in the pathogenesis of CF lung disease." (PMID 40261705, 2025). "Similar findings were described with newer generations of CFTR modulators, with more recent clinical trials including a wider representative population of people with advanced lung disease." (PMID 40144821, 2025). "CFTR modulator drugs have dramatically changed the trajectory of CF disease by significantly improving lung disease and nutrition, as well as reducing sweat chloride concentration as in vivo proof of restored CFTR function in people with CF (pwCF)." (PMID 40978488, 2025). "These quantitative assessments of lung disease in CF have been shown to accurately correlate with improvements in lung disease in patients who have commenced CFTR modulation." (PMID 38397368, 2024). "The degree of correlation between CFTR genotype and phenotype varies, with stronger correlations observed for pancreatic function status compared to lung disease severity." (PMID 38611676, 2024). "Arsenic is associated with lung disease and experimental models suggest that arsenic-induced degradation of the chloride channel CFTR (cystic fibrosis transmembrane conductance regulator) is a mechanism of arsenic toxicity." (PMID 39399016, 2024). "For this reason, expanding endpoints in CF clinical trials include measurements of CFTR protein expression and function as well as lung structure and lung function and finally, lung disease." (PMID 39439894, 2024). "CFTR modulators will be instrumental for younger pwCF to prevent pathogen colonization and subsequent progressive lung disease." (PMID 38442240, 2024). "Forty-one P. aeruginosa isolates were collected on three to four occasions over a 2-year period from five CFTR modulator-naïve adolescents and young adults who were suffering from advanced to end-stage CF lung disease." (PMID 39239637, 2024). "Despite the small sample size, the findings in this study have given important insights into the nature of chronic P. aeruginosa infection in pwCF with advanced lung disease after CFTR modulation." (PMID 38442240, 2024). "In virology, multi-target compounds have been developed for pulmonary diseases targeting F508del-CFTR and PI4KIIIβ." (PMID 39338380, 2024). "Environmental factors and genetic modifiers likely play a significant role in modulating the severity of lung disease in CF patients, as suggested by the weak correlation between CFTR genotype and lung phenotype." (PMID 38611676, 2024).
lung disease (continued). "Data were collected from 12 individuals with a mean age of 36 years, who had advanced lung disease, and at least one copy of F508del-CFTR (42% homozygous, 58% heterozygous)." (PMID 36986509, 2023). "Carnovale and collaborators also assessed the effects of ETI therapy for one year in 26 PwCF homozygous for F508del-CFTR with advanced lung disease (median age of 31.1 years)." (PMID 36986509, 2023). "Changes in ppFEV1, BMI, frequency of pulmonary exacerbations, and adverse effects were assessed in 20 PwCF carrying at least one copy of F508del-CFTR and advanced lung disease." (PMID 36986509, 2023). "Taken together, these studies provide strong evidence of the therapeutic effects of ETI for PwCF who have at least one copy of F508del-CFTR and advanced lung disease, indicating that this CF population can benefit clinically from this therapy." (PMID 36986509, 2023). "Together, Muilwijk’s and our findings suggest that younger patients with more severe lung disease experience higher gains in ppFEV1 in response to CFTR modulation." (PMID 37469865, 2023). "We aimed to investigate the effect of CFTR modulators on structural lung disease progression using different quantitative CT analysis methods specific for people with CF (PwCF)." (PMID 37113757, 2023). "In this manuscript, we utilized a floxed Cftr mouse model to investigate the mechanism driving TGFβ-dependent lung disease in CF, specifically examining the role of CFTR function in smooth muscle and AHR." (PMID 37568151, 2023). "Mutant CFTR expressed in phagocytic cells such as macrophages contributes to persistent infection, inflammation, and lung disease in CF." (PMID 35887098, 2022). "The therapeutics available for treating CF lung disease include antibiotics, mucolytics, bronchodilators, physiotherapy, and most recently CFTR modulators." (PMID 35668939, 2022). "CFTR is expressed in surface epithelia of proximal and distal airways, and dysfunction at those sites likely also contributes to CF lung disease." (PMID 35324331, 2022). "Lung disease severity is highly variable among pwCF, with CFTR, the environment, and modifier genes all contributing to this variability." (PMID 35372502, 2022). "For this reason, it is essential that CFTR modulator treatment is introduced from an early age before irreversible lung disease is established." (PMID 35408875, 2022). "In summary, our outcomes suggest that the administration of combinations of CFTR modulators capable to target different CFTR defects is the best strategy to address the CF pulmonary disease." (PMID 36232697, 2022). "CFTR/ENaC cross-talk disruption, possibly based on ENaC deregulation and/or molecular lesions, has been proposed to contribute to CF lung disease and/or to CFTR-related disorders (CFTR-RD)." (PMID 35462606, 2022). "In light of the fact that CFTR is a transmembrane channel transporter for chloride and bicarbonate, CF lung disease pathogenesis reflects abnormal ion transport." (PMID 36142171, 2022). "CF was one of the first diseases to be considered for gene therapy, and efforts focused on treating CF lung disease began shortly after the CFTR gene was identified in 1989." (PMID 36304167, 2022). "With the latest approval of the triple combination treatment for most people with CF by the FDA, we should expect more people with serious CF pulmonary disease to benefit from CFTR modulation." (PMID 34268058, 2021). "In fact, a better understanding of CFTR mechanisms can not only assist in the design of improved therapies for CF but also identify factors that work in other lung diseases, such as COPD or disseminated bronchiectasis." (PMID 34782688, 2021). "Remarkably, even in the era of CFTR modulation therapies, management of lung infections remains challenging, especially for patients with advanced stages of lung disease." (PMID 34971429, 2021). "Treatments that target the CFTR molecular defect are needed to halt the chain of events that leads to progressive lung disease." (PMID 34268058, 2021).
lung disease (continued). "Previous studies showed that CFTR modulator therapy with lumacaftor-ivacaftor (LUM/IVA) in Phe508del-homozygous patients with CF results in improvement of pulmonary disease and thriving." (PMID 33808590, 2021). "Nowadays, in the new era of CF care with the introduction of CFTR modulators, the progression of lung disease has slowed down and FEV1 has become a less sensitive outcome measure." (PMID 34768401, 2021). "Unfortunately, even in the era of CFTR modulation therapies, management of pulmonary infections in CF remains highly challenging especially for patients with advanced stages of lung disease." (PMID 34971429, 2021). "Because increased inflammation is already present early in life in CF, these findings suggest that inflammation-enhanced CFTR rescue is relevant to early CF lung disease." (PMID 33859562, 2021). "A review summarizing published literature from clinical trials and case series reported a beneficial impact of CFTR modulators on clinical outcomes for pwCF with severe lung disease." (PMID 33917386, 2021). "By studying the clinical effects of CFTR modulator therapy and its impact on the airway microbiome, we will better understand the interplay between CFTR function, the pathogenesis of CF lung disease, and airway infections." (PMID 33816324, 2021). "Bearing in mind the delayed progression of CF lung disease and upcoming highly effective CFTR modulator therapy as mentioned in the introduction, sensitive outcomes to detect early and/or small changes are most needed." (PMID 34348676, 2021). "Addition of a functioning CFTR gene into affected airway cells has the potential to be an effective treatment for lung disease." (PMID 34084147, 2021). "Treatment of F508del CFTR mice with a diet enriched in ω-3 PUFA reduces lung disease, however, a recent Cochrane meta-analysis of five limited trials did not indicate that ω-3 PUFA dietary supplementation is beneficial for CF patients." (PMID 33613309, 2021). "Defects in CFTR lead to a lung disease that is characterized by airway obstruction, persistent bacterial infection, and vigorous neutrophilic inflammation." (PMID 33805605, 2021). "This study demonstrates that SFPQ is a central player in regulating mutant F508del-CFTR in CF lung disease." (PMID 34404863, 2021). "The advent of CFTR modulators represents a significant revolution in CF care and is likely to alter the phenotype of CF lung disease." (PMID 33813719, 2021). "Dysfunction in CFTR leads, among others, to endobronchial infection, exaggerated pulmonary inflammation and airway obstruction that results in progressive lung disease." (PMID 34943888, 2021). "In his review on monozygotic twins (in comparison to dizygotic twins), Cutting reported a maximal 25% impact of the CFTR genotype on lung disease." (PMID 33193670, 2020). "Heritability studies of twins and siblings estimated that at least 50% of lung disease variability is attributable to non-CFTR genetic modifiers." (PMID 33253230, 2020). "Specific to CF, aerosolization of ASOs has shown promise as an effective delivery modality to CFTR expressing lung epithelial cells in both a CF-like lung disease model in mice as well as CF patients." (PMID 32520327, 2020). "A recently published study of siblings with different lung disease manifestations but an identical CFTR genotype predicting severe disease (p.Phe508del/CFTRdele2,3) generated WGS data that were informative." (PMID 32276344, 2020). "LUM and IVA combination have a tremendous role in lung disease as they enhance the CFTR epithelial ion transport, increased ciliary beat, clearance with increased airway surface liquid penetration, and decrease mucous viscosity." (PMID 33520477, 2020). "The FDA-approved modulators partially restore CFTR function and slow down the progression of CF lung disease by increasing processing and delivery to the plasma membrane and improving activity of F508del-CFTR Cl- channels." (PMID 32117984, 2020).
lung disease (continued). "This SNP has the potential of a modifier gene for phenotyping severity of CF lung disease, in addition to the CFTR genotype." (PMID 33193670, 2020). "They displayed improved FVC and FEV1 and increased BMI, and good CFQR score in CFTR-residual function muts and severe lung disease." (PMID 33520477, 2020). "Understanding the pathology of early lung disease as it appears today will be key to maximizing long-term benefits from subsequent CFTR modulator therapies." (PMID 32318073, 2020). "The data presented here point to an important role for B cells and tertiary LF development in CFTR-mediated immune activation and the pathobiology of lung disease in CF." (PMID 31262295, 2019). "CF lung disease exemplifies how the defective functioning of a single ion channel, i.e., CFTR, results in serious disturbances in ASL physiology." (PMID 31396541, 2019). "A pig model of CF lung disease has demonstrated that airway surface liquid (ASL) is more acidic in CF due to defective bicarbonate transport than in those with normal CFTR function resulting in reduced bacterial killing." (PMID 30914718, 2019). "They develop human-like lung disease and CFTR-dependent secretion in trachea, albeit the amiloride-sensitive transepithelial PD was unaltered between CF and non-CF ferret tracheas." (PMID 30662403, 2018). "The expression of the CACC channel in parallel with the CFTR channel in some mouse organs and the inability of mice to develop “spontaneous” lung disease led investigators to examine the pathology of the CF lung using other animal models." (PMID 30662403, 2018). "Therapeutic interventions acting on channels alternative to CFTR (e.g., ENaC inhibitors) and a study evaluating the impact of sex hormones (estrogen and progesterone) on lung disease are ongoing." (PMID 30290809, 2018). "Our data suggests that inhibition of HDAC activity can control Pa-LPS induced lung disease by modulating NFκB-mediated inflammatory signaling, neutrophil chemotaxis and T-reg-activation by CFTR-dependent and/or independent mechanisms." (PMID 29301535, 2018). "The vision for a child born with CF is that treatment with a proven CFTR gene-addition therapy at birth would prevent that child ever developing CF lung disease." (PMID 30538635, 2018). "Recently generated CFTR knockout and Phe508del mutant pig models exhibit lung disease hallmarks including inflammation, airway obstruction, and infection, traits that will facilitate both basic and pre-clinical airway-related research." (PMID 29609604, 2018). "Soon after the CFTR gene was discovered and cloned, gene therapy was proposed to cure lung disease in CF." (PMID 27656143, 2016). "For example, cftr−/− mice developed following the discovery of CFTR lack key features of lung disease seen in the human." (PMID 27025615, 2015). "Mutations in the cystic fibrosis transmembrane conductance regulator (CFTR) gene lead to loss of chloride, sodium and water transport, impaired mucus removal, obstructed airways, chronic infection and end stage lung disease." (PMID 25505695, 2014). "Future studies should evaluate the contribution of manganese to lung diseases but our data shows that manganese decreases the expression of CFTR in bronchial epithelial cells." (PMID 24957904, 2014). "To date, transgenic mice with CF transmembrane conductance regulator (CFTR)-defects relating to CF and lung disease have been established." (PMID 24065108, 2013). "CF is caused by mutations in the CF transmembrane conductance regulator (CFTR) gene, of which CF lung disease is the major cause of morbidity and mortality in these patients." (PMID 23355837, 2013). "Patients with “Classic CF”, presenting earlier onset of symptoms, pancreatic insufficiency, severe lung disease and low Shwachman-Kulczycki scores were found to lack CFTR-mediated Cl− secretion (<5%)." (PMID 23082198, 2012).
lung disease (continued). "It is suggested that only 10–35% of CFTR function is needed to positively impact pulmonary disease, therefore the production and residual activity of mutant CFTR is relevant for clinical outcomes." (PMID 22973227, 2012). "Finally, by assessing lung function prior to the acquisition of the infectious organism analyzed, we were able to evaluate whether the association between predicted CFTR function and infection status was dependent on the severity of lung disease around the time of first infection." (PMID 20932301, 2010). "The protective effect conferred by residual CFTR function is diminished in CF patients with more advanced lung disease." (PMID 20932301, 2010). "Restoration of corrected CFTR function to the airway epithelium of CF patients by delivering a new CFTR gene to airway epithelial cells has long been envisioned as a therapeutic strategy for CF lung disease." (PMID 19621064, 2009). "To date, a relationship between CFTR genotypes and severity of pulmonary disease has proven difficult to determine." (PMID 19909502, 2009). "A relationship between CFTR genotype and severity of pulmonary disease in CF has proven difficult to establish." (PMID 17137500, 2006). "Of even greater interest, our results suggest that the CFTR genotype plays an important role in determining the longitudinal functional progression of lung disease in CF." (PMID 17137500, 2006). "It now appears clear that CFTR modulators commenced in individuals aged >12 years, and therefore with ‘lipotic’ pancreases, cannot prevent progression to diabetes despite their transformative impact on CF-related pulmonary disease." (PMID 41076452, 2026). "This case suggests that the therapeutic intervention for a case of CFTR dysfunction in Asian countries should be performed as early as possible because the prognosis of CFTR pulmonary disease in these regions may be poor." (PMID 40718166, 2025). "Thus, while differences remain, key features impacting CFTR functional measures and lung disease in pwCF are similarly captured in HNE and HBE cultures further validating the use of HNE as a HBE surrogate in this setting." (PMID 40978488, 2025). "Patients who began CFTR modulator therapy after developing advanced lung disease may still experience disease progression, ultimately reaching end-stage lung disease and requiring transplantation." (PMID 40144821, 2025). "For example, the humanized G551D CF rat model may prove a valuable tool for studying CF kidney disease, as it spontaneously develops lung disease, responds to the CFTR modulator Ivacaftor, and offers an appealing husbandry profile for reproduction and cost." (PMID 40807208, 2025). "Based on our observation that CFTR+ AT2 cells are lost in some lung diseases, we expanded our analysis to chronic lung diseases in adults by examining published data sets containing cohorts of chronic obstructive pulmonary disease (COPD) and idiopathic pulmonary fibrosis (IPF) patients." (PMID 41278997, 2025). "This CFTR modulator has not only improved the quality of life and survival outcomes for many pwCF but has also significantly altered the trajectory of advanced lung disease in CF." (PMID 40144821, 2025). "In this review, we summarise the evidence for neutrophilic inflammation in CF lung disease in order to address whether neutrophilic inflammation and high, uncontrolled NSP levels play a similar role in CF lung disease in the era of CFTR modulator therapy." (PMID 39293854, 2024). "We hypothesized that the severity of lung disease in CF correlates with the amount of PGE2 released, which in turn is related to the severity of the mutated CFTR and further regulated by the presence of some COX polymorphisms." (PMID 38610815, 2024). "The coexistence of the 5T variant on the same chromosome results in a non-functional CFTR protein, leading to the onset of lung disease." (PMID 38611676, 2024).